ALB (albumin)
Diseases named in the same sentence as ALB in open-access papers (continued):
Sharing a sentence is not in itself a finding about the gene and the disease.
Hypomagnesemia (18 papers, 2010 to 2025). An abnormally decreased magnesium concentration in the blood. "A large study found that hypomagnesemia (< 1.9 mg/dl) conferred an increased risk of mortality solely in the presence of low-serum albumin levels (< 35 g/l)." (PMID 30977017, 2019). "Our study showed worse 3-year cumulative overall survival for all-cause and CV death in patients with hypomagnesemia (Mg < 2.4 mg/dl); however, the significance was lost when serum albumin quartile was incorporated in the models." (PMID 30977017, 2019). "Although our study showed that PPI use is a risk factor of hypomagnesemia in HD patients, age, albumin, and body mass index were also significantly associated with hypomagnesemia." (PMID 26618538, 2015). "The use of low-Mg dialysate and lower serum albumin levels can easily cause hypomagnesemia." (PMID 38093238, 2023). "In females, low serum albumin levels were associated with hypomagnesemia." (PMID 34416890, 2021). "Serum albumin was found to be independently associated with hypomagnesemia in our study." (PMID 27023783, 2016). "Increase of glomerular filtration of albumin can lead to high amount of Mg, resulting in hypomagnesemia." (PMID 32489951, 2019). "Our findings revealed that hypomagnesemia was associated with lower hemoglobin levels, independent of age, sex, disease duration, BMI, albumin, calcium, eGFR, and PTH in PHPT patients." (PMID 34873402, 2021). "Hypomagnesemia is associated with lower hemoglobin, independent of albumin, calcium, eGFR, and PTH in PHPT patients." (PMID 34873402, 2021). "In multivariate regression analysis, variables associated with increased risk of 30-day mortality include age > 75 years, BUN> 20 mg/dl, albumin < 3 g/dl, inorganic phosphorus levels> 4.5 mg/dl and abnormal levels of magnesium (hypermagnesemia, including high normal levels and hypomagnesemia)." (PMID 30587164, 2018). "The authors pointed out that observation of hypomagnesemia in critically ill patients depends on the Mg fraction measured, and reliable serum ionized Mg concentrations can only be obtained by direct measurement, rather than by calculation from serum total Mg and albumin." (PMID 26566403, 2015).
intestinal obstruction (18 papers, 2018 to 2025). Blockage of the normal flow of the intestinal contents within the bowel. "Among these, 25% to 40% develop malnutrition (serum albumin < 35 g/L), while 15% to 20% require treatment discontinuation due to electrolyte imbalances or bowel obstruction." (PMID 41568006, 2025). "After controlling for hematocrit, total protein, phosphorus, globulin, and albumin, the direct effects remained largely unchanged: intestinal obstruction (2.3-fold increase, p < 0.001), impaction (2.6-fold increase, p < 0.001), and diarrhea (3.0-fold increase, p < 0.001)." (PMID 41321579, 2025). "Inflammatory-related indicators, such as neutrophil, platelet, lymphocyte counts and albumin levels, would largely deviate from the general level in a setting of bowel obstruction or perforation, therefore, patients with bowel obstruction or perforation were excluded from our analysis." (PMID 34238262, 2021). "Therefore, in patients with low albumin concentration, large diameter of the bezoar, longer obstruction time, longer duration of intestinal wall ischemia, and presence of strangulated intestinal obstructions, timely transnasal ileus tube application or surgical treatment is a safer choice." (PMID 33061959, 2020). "In recent years, some studies have shown that ischemia-modified albumin, citrulline, and smooth muscle actin (SM22) levels can be used to diagnose strangulated intestinal obstruction." (PMID 33623822, 2021).
periodontal disease (18 papers, 2013 to 2025). "This study examined the association of salivary albumin and adiponectin with the interaction between bariatric surgery and periodontal disease." (PMID 37047877, 2023). "For this reason, this study aimed to provide current evidence on the prevalence of periodontal disease among undernourished participants and analyze the association between PDs and undernutrition, using body mass index (BMI) and serum albumin level (Alb) in a sample of Yemeni population." (PMID 35265136, 2022). "Further studies with larger samples sizes are necessary to determine whether serum levels of albumin can be used as a diagnostic factor for periodontal diseases." (PMID 35919773, 2018). "A review focusing exclusively on epidemiological studies found that patients with periodontal disease had lower serum albumin levels compared to healthy individuals, which supports the findings of this study." (PMID 40290655, 2025). "Research has demonstrated that serum albumin levels serve as a vital indicator of periodontal disease progression in elderly individuals." (PMID 40290655, 2025). "According to some studies, salivary antioxidant levels, including uric acid, albumin, and ascorbic acid, are reduced in patients with periodontal disease." (PMID 39758261, 2024). "Consequently, it is very important to study the association between periodontal disease and total protein, serum albumin, and globulin levels, which reflect the general health status of an individual who may be at higher risk of developing inflammatory conditions or disorders." (PMID 37809241, 2023). "Previous study comparing the saliva protein components of healthy and periodontal disease individuals found increased serum albumin, hemoglobin, immunoglobulin, and lower abundance of cystatin in the saliva of those with periodontal disease." (PMID 32349305, 2020). "Many investigators have paid special attention to the relationship between periodontal disease and serum albumin levels." (PMID 31382656, 2019). "The results of the present study showed an inverse relationship between serum albumin levels and periodontal diseases." (PMID 35919773, 2018). "Albumin is a protein whose serum levels decrease in inflammatory conditions such as periodontal diseases." (PMID 35919773, 2018). "The results of the present study confirmed the results of all the previous studies that have evaluated the relationship between serum albumin levels and periodontal disease." (PMID 35919773, 2018). "Additionally, serum albumin concentration was found to be inversely related to the presence of periodontal disease in elderly subject and patients who were receiving chronic outpatient hemodialysis." (PMID 40290655, 2025). "In contrast, serum albumin exhibited an inverse association (OR = 0.76, 95% CI: 0.62–0.93, p = 0.011), with lower albumin levels linked to greater odds of periodontal disease, consistent with its role as a negative acute-phase reactant." (PMID 41463003, 2025). "The findings of this study underscore the potential of routinely measured hematological and biochemical parameters—such as white blood cell count, serum albumin, and mean corpuscular hemoglobin concentration (MCHC)—as accessible indicators of systemic alterations associated with periodontal disease." (PMID 41463003, 2025). "Conversely, periodontal disease has also been observed to influence serum albumin concentrations." (PMID 40290655, 2025). "The authors hypothesized that there might be an inverse relationship between periodontal disease and serum albumin concentration." (PMID 37047877, 2023). "Another study regarding albumin levels supports these results and found that there might be an inverse relationship between periodontal disease and serum albumin concentration." (PMID 35225864, 2022). "In addition, another report suggested that serum albumin levels increased following treatment of periodontal diseases (mean/SD: 3.15/0.30 to 3.38/0.37 g/dL) in 30 patients with HD." (PMID 31382656, 2019).
periodontal disease (continued). "Serum albumin levels and clinical variables of periodontal disease (probing pocket depth, gingival index, bleeding index, clinical attachment level and plaque index) were determined before treatment and three months subsequent to non-surgical periodontal treatment." (PMID 35919773, 2018). "As albumin accounts for approximately 75% of colloid osmotic pressure, a decrease in albumin levels during chronic inflammation may lead to osmotic imbalance, affecting bone metabolism and the local tissue environment in periodontal disease." (PMID 40290655, 2025). "Thus, periodontal disease seems to decrease serum albumin level in patients with HD." (PMID 31382656, 2019). "Thus, several reports have indicated a positive correlation between longer dialysis duration and periodontal disease-related parameters in HD patients, and a multivariate analysis model including age, DM, smoking status, and serum albumin level confirmed these findings." (PMID 31382656, 2019). "anginosus can exhibit cytotoxicity in the presence of serum albumin in, for example, the GCF and lesions of gingivitis and periodontal disease." (PMID 37608082, 2023). "While severity of periodontal disease was found to increase with stages of CKD, serum albumin levels declined as periodontal disease severity increased." (PMID 30754693, 2019). "We hypothesize that individuals with periodontal disease exhibit higher WBC counts, lower serum albumin levels, and higher MCHC values, potentially due to systemic inflammatory and hematologic responses associated with chronic periodontal inflammation." (PMID 41463003, 2025). "This study was designed to evaluate the effects of periodontal disease and non-surgical periodontal treatment on serum albumin levels." (PMID 35919773, 2018). "Individuals with periodontal disease had significantly higher WBC counts (p = 0.002) and lower serum albumin levels (p = 0.002) compared with those without periodontal disease, while MCHC demonstrated a borderline, non-significant elevation among participants with periodontal disease (p = 0.052)." (PMID 41463003, 2025). "Moreover, ischemia-modified albumin is a marker of systemic inflammation in periodontal disease, showing a significant decrease following non-surgical periodontal therapy." (PMID 40290655, 2025). "However, BMI, khat chewing, and albumin level were nonsignificant factors of periodontal diseases among Yemeni participants (P > 0.05)." (PMID 35265136, 2022). "This study was undertaken to evaluate changes in serum albumin levels in patients with and without periodontal diseases prior and subsequent to non-surgical periodontal treatment and its relationship with clinical parameters of periodontal disease." (PMID 35919773, 2018). "In contrast tooth loss in elderly adults may reflect poor nutritional status, expressed as low BMI and low albumin level, rather than the presence of periodontal disease." (PMID 23812101, 2013). "The Neutrophil-Percentage-To-Albumin Ratio (NPAR) has been identified as a promising biomarker for systemic inflammation, but its relationship with periodontal disease has not been thoroughly investigated." (PMID 40290655, 2025). "To date, no NHANES-based study has jointly examined WBC, serum albumin, and MCHC in relation to periodontal disease." (PMID 41463003, 2025). "Specifically, WBC count demonstrated a positive nonlinear component (nonlinear p = 0.010), serum albumin showed evidence of nonlinearity (p = 0.028), and MCHC also exhibited a nonlinear pattern (p = 0.031), confirming deviations from linearity in their relationships with periodontal disease." (PMID 41463003, 2025).
angina (17 papers, 2008 to 2026). "Furthermore, the STEMI group had significantly higher fasting sugar, hemoglobin, total WBC/neutrophil/monocyte/lymphocyte counts, CK-MB, and troponin I, and lower HDL-C, eGFR, and albumin than the stable angina group." (PMID 38250610, 2024). "There is a connection between the content of human serum albumin (HSA) in plasma and some diseases, such as kidney or chronic liver diseases and unstable angina in addition the enhancement of albumin in cerebrospinal fluid (CSF) samples of amyotrophic lateral sclerosis (ALS) patients was reported." (PMID 22645474, 2012). "Moreover, the ACS group had significantly higher levels of LDL-C, total cholesterol, total WBC count, neutrophils, monocytes, lymphocytes, creatine kinase-MB, troponin I, and fasting blood glucose, along with lower levels of albumin, eGFR, and HDL-C compared to the stable angina group." (PMID 40303486, 2025).
celiac disease (17 papers, 2012 to 2025). An autoimmune genetic disorder with an unknown pattern of inheritance that primarily affects the digestive tract. "BMI, Albumin and calcium blood levels were important indicators in determining the progress of coeliac disease as linked with other etiological correlations including socio demographic elements." (PMID 23164160, 2012). "Decreased albumin and total protein concentrations can be found in cases of malabsorption syndrome including celiac disease and pancreatic insufficiency." (PMID 35310743, 2022). "Another recent study demonstrated that an increased CRP/albumin ratio can predict coronary microvascular dysfunction better than CRP or albumin alone in patients with celiac disease." (PMID 33453709, 2021). "We evaluated a change in patient model for end-stage liver disease (MELD)-Na and albumin level from the time of celiac disease diagnosis to six months later, after implementing a gluten-free diet." (PMID 32582496, 2020). "Our findings of lost epithelial HSPG will contribute to the increased albumin leak in coeliac disease." (PMID 25198673, 2014). "Since albumin and globulins play an essential role in immunity and inflammation processes, we speculate that an elevation in globulins could be a helpful marker for detecting silent/subclinical celiac disease." (PMID 36778054, 2023). "One study found that patients with celiac disease and SIBO exhibited signs of malabsorption—such as lower levels of hemoglobin, β-carotene, and albumin, and higher levels of fecal fat—compared to patients with celiac disease who did not have SIBO." (PMID 39770940, 2024).
endometrial cancer (17 papers, 2010 to 2025). Primary or metastatic malignant neoplasm involving the endometrium (mucous membrane that lines the endometrial cavity). "The PNI, calculated as 10 × serum albumin (g/dL) + (0.005 × total lymphocyte count/mm3), is associated with increased recurrence risk and shorter survival in breast, prostate, and endometrial cancers." (PMID 40870429, 2025). "Serum albumin (ALB) concentration is strongly associated with OS in patients with endometrial cancer." (PMID 37505298, 2024). "In endometrial cancer, serum albumin levels and inflammatory markers have also been confirmed to be associated with patient survival." (PMID 41383336, 2025). "And this indicates that high concentrations of KRT6A serum albumin (ALB) are closely related to the occurrence and development of OS in patients with endometrial cancer." (PMID 37505298, 2024). "This impact was supposed to affect postoperative serum albumin, prealbumin, and total proteins in endometrial cancer patients undergoing laparoscopic surgery." (PMID 37107783, 2023). "In particular, the serum albumin (ALB) level, a representative and easily obtained biomarker, was considered in previous studies to be an independent prognostic factor for endometrial cancer." (PMID 36428725, 2022). "Low levels of ALB and high levels of fibrinogen, NLR, and CA125 were identified as risk factors for poor prognoses in patients with endometrial cancer, which is consistent with previous studies." (PMID 36428725, 2022). "Nevertheless, the nomograms for predicting endometrial cancer prognosis created by combining fibrinogen, ALB, NLR, and CA125 levels were found to be highly accurate and have value in clinical applications." (PMID 36428725, 2022). "And another study found that endometrial cancer patients with low serum ALB levels had a significantly shorter survival time." (PMID 36685104, 2022). "This study also confirmed the importance of ALB in predicting the prognosis of endometrial cancer, as patients with low ALB levels had worse PFS and OS predictions." (PMID 36428725, 2022). "Similar outcome as the endometrial cancer patients was observed for the two patient groups in terms of serum albumin and PG-SGA score." (PMID 35127741, 2021). "Endometrial carcinoma is one of the common malignant tumors in gynecology, the catabolism of albumin increases accordingly, the amount of albumin required for repairing surgical site increases." (PMID 34126988, 2021). "The aim of this study is to assess the impact of protein supplementation with 20 mg per day before surgery in a prehabilitation program in postoperative serum albumin, prealbumin, and total proteins in endometrial cancer patients undergoing laparoscopic surgery." (PMID 37107783, 2023). "Furthermore, the role of ALB in cancers has been explored, for instance, the endometrial cancer patients with poor overall survival presented low serum ALB concentration, and ALB concentration was the independent prognostic factor for patients." (PMID 35982996, 2022). "Thus, it is necessary to consider ALB as a variable in endometrial cancer prognosis prediction models." (PMID 36428725, 2022). "A good prognostic indicator for resectable colorectal, hepatocellular, and endometrial cancers has been demonstrated to be the inflammation-immunity-nutrition score based on the preoperative hs-CRP, LYM, and ALB composite score." (PMID 40860681, 2025). "Six of them were upregulated in endometrial cancer patients (CLU, SERPINC1, ITIH4, C1RL, APOC3 and DSC1), while ten were downregulated (APCS, C9, APOA1, ALB, APOA4, CFHR1, ITIH2, and ACTB)." (PMID 39194522, 2024). "Fibrinogen (p < 0.0001), ALB (p = 0.031), NLR (p = 0.003), CA125 (p = 0.002), and differentiation (p = 0.034) were independent prognostic factors for OS in patients with endometrial cancer." (PMID 36428725, 2022).
endometrial cancer (continued). "The results indicate that ALB, NLR, and CA125 are important variables for prognosis prediction models of endometrial cancer, which can greatly improve the accuracy of the models." (PMID 36428725, 2022). "Cox regression analysis of haemoglobin, albumin, lymphocyte and platelet (HALP) score categories and endometrial cancer survival outcomes with crude and adjusted hazard ratios and 95% confidence intervals." (PMID 35925991, 2022). "In this study, the fibrinogen, albumin, NLR, and CA125 levels as well as other clinicopathological features of patients with endometrial cancer were recorded." (PMID 36428725, 2022). "Using an LFQ proteomics approach, the exosome proteome from the albumin-depleted serum of early endometrial cancer patients and non-tumor controls was investigated." (PMID 39194522, 2024). "In this study, the easily obtained and representative biomarkers fibrinogen, ALB, and NLR were combined with the common endometrial cancer antigen marker CA125, which comprehensively reflected the systemic state of patients and established effective clinical prediction models." (PMID 36428725, 2022). "Hence, the fibrinogen, ALB, NLR, and CA125 levels were used to establish clinical prognosis prediction models for PFS and OS in patients with endometrial cancer." (PMID 36428725, 2022). "Measures including reasonable control of serum albumin and blood glucose levels, minimally invasive surgery as much as possible, timely assessment of drainage and early removal of the tube may be beneficial to reduce the postoperative SSI in in patients with endometrial carcinoma." (PMID 34126988, 2021).